IGSF3 (immunoglobulin superfamily member 3)
Synonyms: EWI-3; V8; MGC117164; LCDD
Tractability: Antibody: UniProt predicts a signal peptide or a membrane-spanning region. PROTAC: its protein half-life has been measured.
Gene: Protein-coding gene on chromosome 1 (116,574,399 to 116,667,820, reverse strand). Ensembl gene ENSG00000143061.
Subcellular location: Membrane
Subcellular location (Human Protein Atlas): Nucleoplasm; Cytosol
Gene Ontology:
Biological process: lacrimal gland development
Cellular component: cell surface; membrane
Genetic constraint (gnomAD): Loss-of-function variants: 23 observed, 112.85 expected, observed/expected ratio (o/e) 0.2, 90% interval 0.15 to 0.29. The upper end of that interval is the gene's LOEUF score, 0.29, which puts it in group 1 of 6, group 1 being the genes least tolerant of losing a copy. Missense variants: 1,171 observed, 1,612.9 expected, observed/expected ratio (o/e) 0.73, 90% interval 0.69 to 0.76. Synonymous variants: 571 observed, 645.36 expected, observed/expected ratio (o/e) 0.88, 90% interval 0.82 to 0.95.
Homologues: Orthologues: chimpanzee IGSF3 (99% identical), macaque IGSF3 (98% identical), dog IGSF3 (93% identical), guinea pig IGSF3 (93% identical), mouse Igsf3 (93% identical), pig IGSF3 (92% identical), rat Igsf3 (92% identical), rabbit IGSF3 (88% identical), tropical clawed frog igsf3 (55% identical), zebrafish igsf3 (47% identical). Paralogues in human: CD101 (31% identical), PTGFRN (17% identical), IGSF8 (15% identical), VSTM4 (5% identical), VSTM2A (4% identical).
Diseases named in the same sentence as IGSF3 in open-access papers:
IGSF3 is named in the same sentence as 24 diseases in open-access papers, as found by Europe PMC text mining. Sharing a sentence is not in itself a finding about the gene and the disease. The quoted sentences say what the papers report.
glioma (3 papers, 2023 to 2025). A benign or malignant brain and spinal cord tumor that arises from glial cells (astrocytes, oligodendrocytes, ependymal cells). "IGSF-3’s association with synaptic gene sets enriched in glioma patients experiencing seizures suggests its involvement in brain network hyperactivity." (PMID 39201639, 2024). "IGSF3 in glioma inhibits Kir4.1-mediated potassium clearance, leading to neuronal depolarization and epileptiform discharges." (PMID 40777016, 2025). "Functional studies have demonstrated that IGSF-3 drives glioma progression through synaptic remodeling and network hyperactivity by interacting with the potassium channel Kir4.1." (PMID 39201639, 2024). "Another protein, IGSF-3, has been identified as a regulator of glioma progression and brain network hyperactivity." (PMID 39201639, 2024). "Targeting NLGN3 and IGSF-3 could present potential therapeutic strategies to inhibit glioma progression and epileptiform activity." (PMID 39201639, 2024). "In addition, IGSF3 was recently reported to drive glioma progression via synaptic remodeling and brain network hyperactivity." (PMID 37821496, 2023).
COVID-19 (2 papers, 2023). A disease caused by infection with severe acute respiratory syndrome coronavirus 2. "We developed a PRS model for severe COVID-19, which showed that variants detected in ZNF568, GPR173, PCDH15, and IGSF3 were associated with severe COVID-19." (PMID 37547597, 2023).
lung carcinoma (2 papers, 2010 to 2022). "Gene expression of IGSF3 has been linked to the profile of four lung cancer subtypes, setting precedent for its potential as a biomarker." (PMID 35589861, 2022).
atopic dermatitis (1 paper, 2025). "Through systematic computational analysis, this study untangles the core molecular network (SPTLC2, AMD1, IGSF3) and the key metal metabolic regulatory axis (copper homeostasis pathway) involved in the pathophysiology of atopic dermatitis (AD)." (PMID 40564068, 2025).
B-cell lymphoma (1 paper, 2025). "Top proteins specifically associated with non-germinal center-derived B-cell lymphoma included FCMR, SPOCK2, IGSF3 and SEMA4A." (PMID 40894013, 2025).
diabetes (1 paper, 2021). "The importance of fatty liver was particularly striking among the top 30 diabetes-associated proteins (e.g. HGF, IGSF3, IL1RA, ALDH1A1, HNMT, ERBB2 and CDCP1)." (PMID 33279861, 2021). "Another example is IGSF3 which is a little studied member of the immunoglobulin superfamily of proteins that appears to be completely unknown in the context of diabetes and cardiometabolic diseases." (PMID 33279861, 2021). "Although the mechanism that links IGSF3 to diabetes is unclear, there were several observations that makes IGSF3 an interesting candidate to study further, including strong correlations with insulin and liver fat, as well as the responsiveness to diabetes treatment." (PMID 33279861, 2021). "In total there were 44 out of 973 (4.5%) proteins that contributed significantly to the prediction of diabetes (FDR-corrected p<0.05) in the random forest model, the most important being NOS3, HGF, PON3, IGSF3, and ADGRG1." (PMID 33279861, 2021).
hepatocellular carcinoma (1 paper, 2023). A malignant tumor that arises from hepatocytes. "IGSF3 acts as a promoter of hepatocellular carcinoma progression and metastasis through the activation of the NF-κB signaling pathway." (PMID 36980717, 2023).
Insulin resistance (1 paper, 2019). Increased resistance towards insulin, that is, diminished effectiveness of insulin in reducing blood glucose levels. "SGPP2, IGSF3, and VSIG2 are novel biomarkers for the development of insulin resistance." (PMID 30678306, 2019).
kidney failure (1 paper, 2026). An acute or chronic condition that is characterized by the inability of the kidneys to adequately filter the blood. "The strongest association was found for missense variants in IGSF3 (Ig superfamily member 3) associated with the kidney failure versus no kidney failure (P = 1.5 × 10−10)." (PMID 41541775, 2026).
liver cancer (1 paper, 2025). An epithelial or non-epithelial malignant neoplasm that arises from the liver. "Based on the results of single-cell pseudotime analysis, we examined the changes in the expression levels of the shared pathogenic genes (IGSF3, CENPW, CDC6, CDT1) from adjacent non-tumor cells to liver cancer cells during the continuous process." (PMID 40433415, 2025).
tumor (6 papers, 2023 to 2025). "The 1° tumor had eight variants in MKI67, PRKN, PCLO, POLE, CDKN1C, IGSF3, and MED12 genes, which were also present in the brain and spine metastatic cell lines but not present in the parental cell line." (PMID 36900209, 2023). "IGSF3, a gene involved in cell adhesion and signal transduction, its downregulation may hinder normal cell communication, accelerating liver cell degeneration and tumor transformation." (PMID 40433415, 2025). "The essentiality of IGSF3 and SLC2A1 in a significant fraction of HNSC cell lines testifies to their importance to the viability of HNSC tumor cells." (PMID 37835579, 2023).
cancer (3 papers, 2022 to 2023). A tumor composed of atypical neoplastic, often pleomorphic cells that invade other tissues. "Consequently, the ability of these cancer cells to downregulate IGSF3 and SLC2A1 to evade CAR cell killing might be limited, upgrading their potential for serving as future CAR targets in our minds." (PMID 37835579, 2023). "Gene expression analysis across all three cancer types subsequently found a common increase in the expression of five genes (BCAR1, COL1A1, IGSF3, RRAD, and TFPI2), which may further inform biomarker study for identifying CTCs." (PMID 36980717, 2023).
IGSF3 also shares sentences with these, for which no sentence is quoted: Burkitt lymphoma (1 paper); colon carcinoma (1); Granuloma (1); infection (1); malignant lymphoma (1); mastitis (1); metastatic carcinoma (1); Nasolacrimal duct obstruction (1); neuroblastoma (1); ovarian carcinoma (1); sarcoidosis (1); ulcers (1).